METTL16 (methyltransferase 16, RNA N6-adenosine)
Diseases named in the same sentence as METTL16 in open-access papers (continued):
Sharing a sentence is not in itself a finding about the gene and the disease.
colorectal cancer (18 papers, 2021 to 2026). A primary or metastatic malignant neoplasm that affects the colon or rectum. "In the results, we found that METTL16 was highly expressed in colorectal cancer (CRC)and was associated with the prognosis of the disease, so we chose CRC as the cancer to further explore." (PMID 40015977, 2025). "Studies also indicate that METTL16 is associated with poor prognosis in colorectal cancer (CRC), as it binds with IGF2BP1 to significantly increase SOGA1 expression and mRNA stability, contributing to METTL16-mediated glycolysis and CRC growth." (PMID 40271153, 2025). "The high expression of METTL16 in brain cancer, colorectal cancer and ovarian cancer was associated with shorter OS, suggesting that METTL16 plays a carcinogenic role in these tumors." (PMID 40015977, 2025). "Bioinformatics data indicated that METTL16 was overexpressed in most of these human malignancies and was significantly associated with the prognosis of patients with cancer, especially in colorectal cancer (CRC)." (PMID 40015977, 2025). "In colorectal cancer, mutations in key residues of METTL16, such as R200Q or G110C, were found, suggesting the association of METTL16 with the disease." (PMID 37927399, 2023). "There is one documented type of large intestinal cancer which has a mutation (in the methyltransferase domain) that abolishes METTL16’s methylation activity." (PMID 37504262, 2023). "Mutations of crucial METTL16 residues, such as R200Q or G110C, have been reported in large intestinal cancer, potentially implicating METTL16 in the disease." (PMID 33671635, 2021). "In colorectal cancer, METTL16 plays a key role in promoting glycolytic metabolism and tumor progression by regulating the expression of key glycolytic enzymes, such as SOGA1 and pyruvate dehydrogenase kinase 4 (PDK4)." (PMID 41459114, 2026). "Here, we report that an RNA m6A methyltransferase, METTL16, plays an indispensable role in the progression of chromosome segregation and is required to preserve chromosome stability in colorectal cancer (CRC) cells." (PMID 38084791, 2024). "This study explored the biological function of m6A methyltransferase METTL16 in glycolytic metabolism and revealed a new mechanism for the progression of Colorectal cancer (CRC)." (PMID 37340443, 2023). "For example, the database OncoMX demonstrates that METTL16 RNA has shown significant upregulation in kidney and colorectal cancers, but significant downregulation in uterine, bladder, prostate, breast, and lung cancers." (PMID 37504262, 2023). "The expression level of METTL16, together with those of other m6A regulators, affects the prognosis of colorectal cancer patients." (PMID 36158188, 2022). "For example, it was revealed that a poor prognosis of colorectal cancers is associated with a high level of m6A RNA, and in these cells, there is an overexpression of METTL3, METTL16, and WTAP regulatory proteins." (PMID 34357041, 2021). "METTL16 was found to be overexpressed in colorectal cancer and to be underexpressed in hepatocellular carcinoma, affecting activation of multiple metabolic pathways." (PMID 34589481, 2021). "Furthermore, a colorectal cancer cell/T-cell co-culture system demonstrated that overexpression of METTL16 in colorectal cancer cells partially inhibits the proportion of PD-1-positive activated T cells." (PMID 41459114, 2026). "Our findings reveal novel insights into METTL16 expression and its biological functions in diverse cancer types, indicating that METTL16 could serve as a prognostic biomarker and plays an important role in colorectal cancer." (PMID 40015977, 2025). "The expression level of METTL16, together with other m6A regulators, such as METTL3, METTL14, FTO, and ALKBH5, affect the outcome of colorectal cancer (CRC) patients." (PMID 33671635, 2021). "Besides, ALKBH5, FTO, METTL3, METTL14, METTL16 and WTAP were detected in a section of colorectal cancer tissue." (PMID 39039912, 2024).
hepatocellular carcinoma (17 papers, 2021 to 2026). A malignant tumor that arises from hepatocytes. "In hepatocellular carcinoma, studies have linked CNV changes in genes such as KIAA1429 (also known as vir-like m6A methyltransferase-associated protein (VIRMA)) and METTL16 to hepatocellular carcinoma development, progression, and clinical prognosis." (PMID 41459114, 2026). "In this way, METTL16 plays a critical regulatory role in ferroptosis in hepatocellular carcinoma by modulating the expression and function of SENP3 and LTF." (PMID 41459114, 2026). ",108, 109 In hepatocellular carcinoma, METTL16 enhances the expression of SENP3 mRNA by catalyzing its m6A modification." (PMID 41459114, 2026). "In hepatocellular carcinoma, METTL16 and METTL3 collaborate to enhance m6A modifications on ZNF706 neighboring transcript 1 (ZNNT1) mRNA, thereby increasing its stability and expression." (PMID 41459114, 2026). "Poor prognosis has been observed owing to downregulation of METTL16 in patients with hepatocellular carcinoma and endocrine system tumors." (PMID 36158188, 2022). "Recently, METTL16 was reported to exert an m6A-independent role in hepatocellular carcinoma cells in vitro, raising a question about whether METTL16 plays an m6A-dependent or m6A-independent role in the development of HSPCs in vivo." (PMID 38605226, 2024). "Additionally, in hepatocellular carcinoma, METTL16 was identified to promote translation in an N6-methyladenosine (m6A)-independent manner." (PMID 37859814, 2023). "Therefore, METTL16 is considered a protective gene that can suppress the development of hepatocellular carcinoma and endocrine system tumors." (PMID 36158188, 2022). "More recently, a similar mechanism was described for METTL16 in hepatocellular carcinoma." (PMID 36012237, 2022). "Furthermore, in hepatocellular carcinoma cells, the depletion of METTL16 produced a strong decrease in translation and impaired cell survival." (PMID 36012237, 2022). "In addition, the translation facilitated by METTL16, which is important in the carcinogenesis of hepatocellular carcinoma, is mediated by the interaction between METTL16 and EIF3A and EIF3B." (PMID 36051357, 2022). "The role of METTL16 in cancer is currently researched mainly on hepatocellular carcinoma." (PMID 34075693, 2021). "Recently, downregulation of METTL16 has been correlated with poor overall survival in patients with hepatocellular carcinoma (HCC) and endocrine system tumors." (PMID 33671635, 2021). "In hepatocellular carcinoma, the HIF-1α/METTL16/lnc-CSMD1-7/RBFOX2 signaling axis has been shown to regulate interactions between tumor cells and the tumor microenvironment, particularly influencing cell behaviors such as epithelial–mesenchymal transition." (PMID 41459114, 2026). "METTL16, through m6A methylation, reduces the RNA stability of lnc-CSMD1-7, which promotes the metastasis and progression of hepatocellular carcinoma." (PMID 41459114, 2026). "Additionally, METTL16 can directly interact with the long non-coding RNA RAB11B antisense RNA 1 (RAB11B-AS1), inducing its m6A modification and reducing the RNA stability of RAB11B-AS1, leading to decreased expression and affecting hepatocellular carcinoma progression." (PMID 41459114, 2026).
lung carcinoma (11 papers, 2020 to 2026). "Conversely, in blood cancer and lung cancer, overexpression of METTL16 was associated with longer OS, suggesting that METTL16 plays a protective role." (PMID 40015977, 2025). "In lung cancer, METTL16 has been shown to interact with eIF4E2, a translation repressor, preventing its interaction with the mRNA 5′ cap structure." (PMID 41459114, 2026). "In lung cancer metastasis, METTL16 regulates the stability of SYNPO2L, mediates the secretion of COL10A1 by cancer-associated fibroblasts (CAFs), and promotes epithelial-mesenchymal transition (EMT), making tumor cells more prone to metastasis." (PMID 41256854, 2025). "In lung cancer, METTL16 interacts with eIF4E2 to enhance the translation of key oncogenes, thereby driving tumor development." (PMID 41256854, 2025). "Previously, studies have investigated the role of thirteen m6A regulatory genes in lung cancer, but the roles of seven newly discovered ones, namely, METTL16, YTHDF3, IGF2BP1, IGF2BP2, IGF2BP3, HNRNPG, and HNRNPA2B1 has not been determined." (PMID 33795529, 2021). "Our data indicated that patients with higher expression of DDX3X/CBS, DDX3X/METTL16 and DDX3X/JUND exhibited poorer overall survival and progression-free interval, suggesting the prognostic value of DDX3X and its associated genes for lung cancer patients." (PMID 40885716, 2025). "As expected, only overexpressing wildtype METTL16 triggers lung cancer cells proliferation." (PMID 40885716, 2025). "Lastly, we uncovered that DDX3X controls METTL16 transcription through a direct interaction with JUND transcripts, thus delineating an intact pathway elucidating how DDX3X regulates lung cancer progression." (PMID 40885716, 2025). "We also looked at the protein levels of RBMX, METTL16, and LRPPRC in lung cancer cells and discovered that RBMX and LRPPRC were upregulated, whereas METTL16 was downregulated in lung cancer cells relative to normal lung epithelial cell BEAS-2B." (PMID 35035657, 2022). "To determine if this a more widespread observation, we also examined METTL16’s localization in a lung fibroblast cell line (CCD34LU) as well as a lung cancer cell line (NCI-H1299) and again found METTL16 to be predominant in the cytoplasm of both cell types." (PMID 31940410, 2020). "Given that JUND is a transcription factor in lung cancer progression, we further investigated whether JUND acts as a nexus between METTL16 and DDX3X." (PMID 40885716, 2025). "Furthermore, we demonstrated that METTL16-dependent m6A modification is essential for DDX3X-regulated CBS expression and lung cancer proliferation." (PMID 40885716, 2025). "Recent studies have unveiled a novel, m6A-independent role of METTL16 that promotes translation and tumorigenesis by interacting with eIF4E2 in lung cancer independent of m6A catalytic activity." (PMID 40734692, 2025).
glioma (10 papers, 2019 to 2026). A benign or malignant brain and spinal cord tumor that arises from glial cells (astrocytes, oligodendrocytes, ependymal cells). "In low-grade gliomas, for example, METTL16 expression has been found to be negatively correlated with the presence of CD8+ T lymphocytes." (PMID 41459114, 2026). "Consistently, we also predicted that METTL16 was overexpressed in gliomas, which was later verified by qRT‐PCR." (PMID 39248438, 2024). "METTL16 knockdown inhibited the migrative and invasive abilities of glioma cells and induced ferroptosis in vitro." (PMID 39248438, 2024). "Both of NFE2L2 and METTL16 are involved in the immune response of low‐grade gliomas, serving as novel therapeutic targets for gliomas." (PMID 39248438, 2024). "Studies have demonstrated that c-MYC can upregulate FDX1 via YTHDF1 with increased sensitivity to cuproptosis in glioma cells and that copper stress promotes METTL16 lactylation, leading to elevated METTL16 expression, which positively mediates cuproptosis through the m6A modification of FDX1 mRNA." (PMID 41373022, 2025). "Interestingly, knockdown of METTL16 significantly diminished migratory and invasive cells, suggesting that METTL16 promoted migration and invasion in glioma cells." (PMID 39248438, 2024). "We therefore speculated that the infiltration of CD8+ T lymphocytes may realize the oncogenic role of METTL16 in low‐grade gliomas." (PMID 39248438, 2024). "NFE2L2 interacted with METTL16 to regulate the immune response in low‐grade gliomas, and both molecules may be novel therapeutic targets for gliomas." (PMID 39248438, 2024). "In addition, knockdown of METTL16 significantly enhanced the content of MDA and ROS level, but inhibited GSH level, suggesting that METTL16 inhibited ferroptosis in glioma cells." (PMID 39248438, 2024). "The level of METTL16 is upregulated in glioma and is correlated with poor prognosis of melanoma." (PMID 37647025, 2023). "Considering METTL16 is also a putative m6A methyltransferase and knockdown of METTL16 could result in approximately 20% decrease of m6A, we also investigated the expression of METTL16 in gliomas with different malignancy status in the CGGA dataset." (PMID 30810537, 2019). "To further explore the correlations of METTL16 and NFE2L2 with the immune microenvironment in gliomas, we compared the abundances of 22 types of tumour‐infiltrating immune cells between low‐grade glioma and normal tissues using the CIBERSORT R script." (PMID 39248438, 2024). "In the UALCAN database, both METTL16 and NFE2L2 were found significantly upregulated in glioma tissues." (PMID 39248438, 2024). "Subsequently, the differential analysis showed that, between glioma and normal brain tissue, a variety of m6A-related genes were differentially expressed, including METTL14, METTL16, ZC3H13, YTHDC1, YTHDC2, YTHDF2 etc." (PMID 35559019, 2022). "Taken together, these results indicated that IGF2BP2, KIAA1429, METTL16, and METTL3, as well as 208 targets are involved in the occurrence of glioma, GBM, and LGG." (PMID 34589481, 2021). "Our results suggested that IGF2BP2, KIAA1429, METTL16, and METTL3, as well as 208 targets are involved in the occurrence of glioma, GBM, and LGG." (PMID 34589481, 2021). "For glioma, we found that IGF2BP2, KIAA1429, METTL16, METTL3, and YTHDF1 are consistently upregulated at the mRNA level of CGGA and GSE16011 datasets (7.97E-05 < FDR < 0.04)." (PMID 34589481, 2021). "A previous bioinformatics study suggested that METTL16 is involved in glioma genesis, but this finding has not been validated in further ex vivo experiments." (PMID 39248438, 2024). "In conclusion, m6A RNA methylation regulators KIAA1429, METTL16, METTL3, IGF2BP2, and YTHDF1, as well as their targets may play a critical role in the occurrence of glioma, which may be beneficial to therapeutic customization and clinical decision-making." (PMID 34589481, 2021).
glioma (continued). "Notably, m6A writers METTL3, METTL16, and KIAA1429 exhibited a cross-talk with the m6A reader YTHDF1 in gliomas, GBM, and LGG." (PMID 34589481, 2021). "Collectively, m6A RNA methylation regulators KIAA1429, METTL16, METTL3, IGF2BP2, and YTHDF, and targets NASP, TIMP1, U2AF2, COL18A1, and VEGFA could serve as oncogenes in glioma, while PHLPP2 is a tumor suppressor." (PMID 34589481, 2021). "In the present study, METTL16 knockdown prominently attenuated the migrative and invasive abilities of LN229 cells, and increased the content of MDA and ROS level, but inhibited GSH level, suggesting that METTL16 may be an oncogene that inhibits ferroptosis in glioma cells." (PMID 39248438, 2024).
acute myeloid leukemia (7 papers, 2024 to 2026). Acute myeloid leukemia (AML) is a group of neoplasms arising from precursor cells committed to the myeloid cell-line differentiation. "Moreover, METTL16 reprograms BCAA metabolism in acute myeloid leukemia cells by modulating the expression of these key enzymes." (PMID 41459114, 2026). "However, acute myeloid leukemia cells are even more dependent on METTL16." (PMID 41459114, 2026). "In this study, we shed light on a novel molecular mechanism whereby METTL16 plays a role in acute myeloid leukemia (AML) progression through an m6A-dependent manner." (PMID 40946103, 2025). "In acute myeloid leukemia (AML), METTL16 drives tumor development by promoting the expression of branched-chain amino acid (BCAA) transaminases BCAT1 and BCAT2, reprogramming BCAA metabolism." (PMID 41256854, 2025).
bladder cancer (7 papers, 2021 to 2025). "In the present study, we sought to investigate the roles and associated mechanisms of METTL16 in bladder cancer." (PMID 38385084, 2024). "Taken together, our results showed that METTL16 was downregulated in bladder cancer and associated with the prognosis of bladder cancer patients." (PMID 38385084, 2024). "First, we used m6A dot blot to explore the role of METTL16 in regulating m6A modification in bladder cancer." (PMID 38385084, 2024). "Together, knocking down PMEPA1 reversed the proliferation and cisplatin-resistance induced by METTL16 knockdown through autophagy pathway in bladder cancer cells." (PMID 38385084, 2024). "METTL16 significantly inhibits bladder cancer cell proliferation through the HIF-2α-METTL16- PMEPA1 autophagy axis in an m6A manner." (PMID 39289775, 2024). "To explore the possible upstream regulatory of METTL16, we simulated the anoxic environment of bladder cancer cells by exposing T24 and UMUC3 cells in 21% (Normoxic) or 1% (Hypoxia) O2." (PMID 38385084, 2024). "Together, HIF-2α down-regulated expression of METTL16 by binding to the METTL16 promoter region in bladder cancer cells under hypoxia." (PMID 38385084, 2024). "In BLCA patients, METTL16 was downregulated in bladder cancer (BLCA) compared to normal tissue adjacent to the cancer." (PMID 39289775, 2024). "Low expression of METTL16 was associated with higher TNM stage and poor prognosis in bladder cancer patients." (PMID 39289775, 2024). "METTL16 was also downregulated in seven bladder cancer cell lines compared with SVHUC-1 (human ureteral epithelial immortalized cell line, as the normal urothelial cell line)." (PMID 38385084, 2024). "First, we analyzed 35 paired bladder cancer tissues and found that the RNA and protein expression of METTL16 in bladder cancer tissues were significantly downregulated compared with paired adjacent tissues." (PMID 38385084, 2024). "In the present study, we found that the level of METTL16 was significantly downregulated in bladder cancer tissues and cell lines." (PMID 38385084, 2024). "METTL16 significantly inhibited bladder cancer cell proliferation and sensitized bladder cancer cells to cisplatin via HIF-2α-METTL16-PMEPA1-autophagy axis in a m6A manner." (PMID 38385084, 2024). "This indicated that METTL16 may regulate the biological function of bladder cancer in a cell cycle independent manner." (PMID 38385084, 2024). "Taken together, all these results indicated that METTL16 may suppress the proliferation and cisplatin resistant of bladder cancer cells through autophagy pathway." (PMID 38385084, 2024). "Our finding indicated that PMEPA1 and METTL16 have co-localization in bladder cancer cells." (PMID 38385084, 2024). "The waterfall plot showed that KIAA1429 and METTL3 presented with the highest mutation frequency, mainly for missense mutations, nonsense mutations, and multiple hits, whereas METTL16 did not present as having any mutation in bladder cancer samples." (PMID 34733275, 2021). "However, the mechanism and role of METTL16 in bladder cancer have yet to be elucidated." (PMID 38385084, 2024). "Further research had also shown that in bladder cancer cells, METTL16 could specifically recognize the m6A sites of the 3'-UTR in PMEPA1 mRNA, which decreased the stability of PMEPA1 mRNA and eventually led to a decrease in the protein level of PMEPA1 in an m6A-dependent manner." (PMID 38385084, 2024). "Besides, CCK-8 and colony formation analysis showed that the increased proliferation of bladder cancer cell lines induced by METTL16 knockdown could be reversed by interference with PMEPA1." (PMID 38385084, 2024). "However, cell cycle analysis revealed that METTL16 knockdown did not cause obvious cycle changes in bladder cancer cells." (PMID 38385084, 2024). "Therefore, we speculated that METTL16 may affect the autophagy pathway of bladder cancer cells." (PMID 38385084, 2024). "Therefore, we speculated that METTL16 acted as a suppressor in bladder cancer." (PMID 38385084, 2024).